Y_RNA (Y RNA )
Gene: Miscellaneous RNA gene on chromosome 1 (151,841,736 to 151,841,837, reverse strand). Ensembl gene ENSG00000201134.
Homologues: Orthologues: chimpanzee Y_RNA (99% identical), macaque Y_RNA (95% identical). Paralogues in human: Y_RNA (91% identical), RNY3 (90% identical), Y_RNA (90% identical), Y_RNA (89% identical), Y_RNA (88% identical), RNY3P1 (87% identical), Y_RNA (87% identical), RNY3P13 (86% identical), Y_RNA (86% identical), RNY3P14 (85% identical), RNY3P16 (85% identical), RNY3P2 (85% identical), and 98 more.